APLN (apelin)
Diseases named in the same sentence as APLN in open-access papers (continued):
Sharing a sentence is not in itself a finding about the gene and the disease.
Insulin resistance (continued). "Moreover, apelin concentration and gene expression in mice has been reported to be regulated according to the severity of insulin resistance, suggesting a link between apelin and glucose homeostasis." (PMID 31548844, 2019). "Lower levels of high sensitivity C-reactive protein, apelin, homeostatic model assessment of insulin resistance (HOMA-IR), and appetite score were observed in the zinc group in comparison with the placebo group (P = 0.0001, 0.001, 0.031 and 0.001 respectively)." (PMID 31827626, 2019). "Furthermore, apelin reduced insulin resistance during a hyperinsulinemic-euglycemic clamp in mice by stimulating glucose uptake in soleus muscle." (PMID 31492821, 2019). "Furthermore, the role of apelin in the development of insulin resistance has also attracted a lot of attention in the recent years." (PMID 31827626, 2019). "These and other lines of evidence demonstrate that apelin may be a potentially viable candidate in the search for treatments for type 2 diabetes and the insulin resistance." (PMID 30526660, 2018). "Apelin null (apelin−/−) mice exhibiting hyperinsulinemia and insulin resistance could be restored by the injection of apelin." (PMID 30526660, 2018). "The results of the current study revealed that cardiacApelin and Apj expression were increased in the HF/HCfed rats and these changes were significantly correlatedwith increased serum levels of Apelin and insulin, bodyweight, insulin resistance, inflammatory markers and theatherogenic lipid profile." (PMID 29845798, 2018). "Since high levels of free fatty acid can lead to insulin resistance, this may help to explain the beneficial role of apelin in regulating metabolic homeostasis, although further study is needed to describe the underlying mechanism." (PMID 24475149, 2014). "The increase in plasma apelin levels may be a result of compensatory response to insulin resistance." (PMID 23772224, 2013). "All together, these data may indicate that the increased apelin levels that we observe in T2D patients could represent a compensatory mechanism to reduce both insulin resistance and impaired insulin-secretion." (PMID 23227256, 2012). "Since TNF-alpha is a marker of low-grade inflammation, which is present in the insulin-resistant state, it could be also seen as a marker of insulin-resistance, as it is for apelin." (PMID 23227256, 2012). "Additionally, the decrease in hepatic levels of fetuin‐A and Gdf15, along with an increase in apelin, might reduce insulin resistance and further support improved glucose metabolism." (PMID 39721028, 2025). "Moreover, reduced APLN levels significantly relate to improvement of insulin resistance." (PMID 33171610, 2020). "When insulin resistance is decreased, this may lead to decreased apelin levels." (PMID 25914650, 2015). "Thus, there is a tissue-dependent regulation of the apelin/APJ system that could also be modified with the severity of insulin resistance (for example in diabetic db/db mice)." (PMID 24244380, 2013). "In insulin-resistant mice, apelin improves mitochondrial biogenesis and enhances mitochondrial function through the AMPK pathway, indicating the potential of apelin in treating insulin resistance." (PMID 39872377, 2024). "Apelin (APLN), as an adipokine, has the function of regulating lipid metabolism and can alleviate insulin resistance by affecting the level of adiponectin (ADPN)." (PMID 38473166, 2024). "The KEGG-enriched pathways obtained include insulin resistance, the PPAR signaling pathway, and the apelin signaling pathway." (PMID 39458990, 2024). "On the contrary, it was reported that cardiac apelin and APJ expression and serum apelin level were increased in obese rats, and downregulation of apelin and APJ expression alleviated insulin resistance and inflammation." (PMID 35355561, 2022).
Insulin resistance (continued). "The relatively high abundance of KEGG pathways predicted by Metascape were insulin resistance, cAMP, PPAR, and Apelin pathways, in which insulin resistance, PPAR signaling pathway, and Apelin signaling pathway contain AMPK/UCP1 pathway." (PMID 35962183, 2022). "The Apelin/APJ pathway is an emerging and promising therapeutic target for treatment of cardiovascular disease, insulin resistance, and type 2 diabetes." (PMID 33171610, 2020). "There was a correlation between insulin (p-value = 0.043), Homeostatic Model Assessment for Insulin Resistance (HOMA-IR)(p-value = 0.045) and apelin gene expression in visceral adipose tissue." (PMID 31548844, 2019). "Serum levels of insulin, Apelin, glucose, tumor necrosis factor-α(TNF-α), interleukin-1β (IL-1β) and the homeostasis model assessment of insulin resistance (HOMA-IR) were alsomeasured using commercial kits." (PMID 29845798, 2018). "This review article focuses on novel adipokines including visfatin, resistin, apelin, vaspin, and retinol binding protein-4 (RBP-4) and addresses their changes after bariatric surgery and their relationship to insulin resistance." (PMID 23772224, 2013). "While none of these studies assessed the relationship between apelin and kidney parameters, these findings show promising results for the treatment of T2D, highlighting the potential of apelin to enhance insulin resistance and delay CKD progression." (PMID 41515992, 2025). "Additionally, pathways such as “Insulin resistance” (KEGG:04931) and “Apelin signaling pathway” (KEGG:04371) were significantly enriched, highlighting the complex regulatory response to maternal overnutrition in muscle tissues." (PMID 39375502, 2024). "Another clinical research showed that physical training increases the apelin level, with a reduction of low-density lipoprotein cholesterol (LDL-C) and hsCRP levels, and insulin resistance, resulting in the decreased progression of the carotid intima–media thickness in patients with type 2 diabetes." (PMID 35355561, 2022). "Apelin increases insulin sensitivity by promoting increased glucose uptake in skeletal muscle, and apelin knockout mice develop hyperinsulinemia and insulin resistance without any apparent differences in body weight." (PMID 31472173, 2019). "O2 consumption and body temperature were also increased in HFD fed Tg-apelin mice but not in obese and insulin resistant mice in response to chronic apelin treatment." (PMID 25914650, 2015). "If PCOS patients, without insulin resistance and BMI < 25, were evaluated, apelin levels would be similar in healthy women." (PMID 25374607, 2014). "In obese and insulin-resistant mice, apelin and APJ expression are increased in adipose tissue but not in skeletal muscles." (PMID 24244380, 2013). "Further support on this relationship is given by the low levels of apelin observed in type 1 diabetic subjects, where insulin secretion is absent and insulin-resistance is usually not present." (PMID 23227256, 2012). "Interestingly, current scientific reports show that visfatin (as well as apelin) in PCOS not only plays a hypoglycemic role, but may also exacerbate inflammation, thus worsening insulin resistance." (PMID 40491594, 2025). "There is also evidence that the level of apelin in the group of fasting pregnant women is significantly higher than non-fasting pregnant women, which is may be related to insulin resistance at they." (PMID 36093083, 2022). "Indeed, plasma apelin levels have been found to correlate negatively, but also positively with HOMA-IR (Homeostatic Model Assessment for Insulin Resistance), and most studies have excluded the existence of any significant association between this adipokine and IR." (PMID 31505789, 2019). "Increased concentrations of apelin in type 1 diabetes could be an attempt to compensate for the lack of insulin and to overcome insulin resistance." (PMID 25914650, 2015).
Insulin resistance (continued). "Apelin levels were higher in non-obese PCOS patients, suggesting a compensatory mechanism for metabolic consequences of insulin resistance." (PMID 27473078, 2017).
type 2 diabetes (71 papers, 2012 to 2026). "One Chinese study reported a strong relationship between apelin gene single nucleotide polymorphisms and type 2 diabetes." (PMID 41515992, 2025). "Long-term apelin-13 administration can prevent pancreatic beta cell loss or dysfunction in type 2 diabetic rat models and reduce myocardial fatty acid uptake and oxidation through inhibiting the PPAR-α receptor." (PMID 35355561, 2022). "For lipid metabolism, inhibition of adipogenesis and lipolysis by apelin was documented and a significant association between apelin and triglycerides (TG) was revealed in morbidly obese patients with type 2 diabetes." (PMID 31217908, 2019). "In the hypothalamus, chronic exposure to high levels of apelin is associated with an increase in hepatic glucose production, and then contributes to the onset of type 2 diabetes." (PMID 27549402, 2016). "Considering that most patients with type 2 diabetes are thin after disease onset, resulting in reduced size of adipose tissue, which may be associated with low serum Apelin." (PMID 35610700, 2022). "The finding of a population-based study demonstrates that high apelin concentration was associated with reduced incidence of type 2 diabetes risk; thus, it is implied that apelin may have a protective effect against metabolic disorders." (PMID 34660801, 2021). "We evaluated the association of apelin levels with mortality and hospitalization events, as well as the relationship of apelin with renal function and cardiovascular risk factors, in a homogeneous population of type 2 diabetic patients with a diagnosis of mild to moderate CKD." (PMID 24089668, 2013). "The prognostic value of apelin in DKD was evaluated in a prospective observational study of 150 patients with type 2 diabetes and CKD at any stage." (PMID 41515992, 2025). "In patients with type 2 diabetes, serum APLN concentrations were observed in markedly higher concentrations, as compared with healthy subjects." (PMID 40182840, 2025). "Aerobic exercise realized four times a week, with each session lasting 60 min, by patients living with type 2 diabetes for 12 weeks (60–75% maximal heart rate) supports an increase in apelin secretion, but this effect was only reported in women." (PMID 40943107, 2025). "A clinical study showed that type 2 diabetes and DN were related with decreased serum Apelin levels." (PMID 39014438, 2024). "Recently, an interesting study transduced WJ-MSCs with apelin-expressing lentiviral particles, and those genetically modified cells were injected into the type 2 diabetes rodent model." (PMID 38178017, 2024). "The descreased Apelin level was also suggested to be a potential biomarker for diabetic nephropathy in patients with type 2 diabetes." (PMID 39014438, 2024). "In the treatment of type 2 diabetic rats, Apelin substantially reduced gene expression and increased the expression of CD36CPT-1 and PPAR-α in the heart fatty acid transporter." (PMID 36611783, 2023). "Several studies have demonstrated an increase in plasma concentrations of apelin in patients with type 1 or type 2 diabetes." (PMID 37424869, 2023). "Similar results on pancreatic β-cell mass have been obtained in the HFD-fed STZ-induced experimental type 2 diabetic rats receiving a once-daily intraperitoneal injection of apelin (0.1 μmol/kg) for 10 weeks." (PMID 35628332, 2022). "In a rat model of type 2 diabetes with a high-fat diet, apelin-13 reduces serum total cholesterol, triglyceride, and LDL-C and increases high-density lipoprotein cholesterol (HDL-C)." (PMID 35355561, 2022). "Serum apelin is higher in diabetes type 2 patients as compared to healthy individuals and it is positively correlated to urinary albumin excretion." (PMID 34206927, 2021). "Recent studies have highlighted the paramount importance of apelin and its receptor, since they have been proposed as a valuable new treatment target in type 2 diabetes." (PMID 34127923, 2021).
type 2 diabetes (continued). "It’s necessary to analyze the role of VEGF, apelin, and HO-1 in patients with type 2 diabetes (T2DM), and to evaluate its relevance to diabetic retinopathy (DR)." (PMID 32770964, 2020). "Based on this evidence, apelin appears be a relevant indicator for metabolic syndrome and related to type 2 diabetes." (PMID 30696454, 2019). "It had been demonstrated that apelin played a vital role in the pathophysiology of many diseases, including cardiovascular disease, renal disease, type 2 diabetes, and tumors." (PMID 31270645, 2019). "The aim of this study is to create a new approach to treat type 2 diabetes by inducing prolonged expression of apelin in Wharton’s jelly-derived mesenchymal stem cells (WJ-MSCs)." (PMID 30526660, 2018). "Type 2 diabetic rats were infused with either WJMSCs-apelin (2 × 106 cells) or an equivalent dose of saline through the tail vein injection 7 days after STZ injection." (PMID 30526660, 2018). "In conclusion, the present study has shown a new approach that combines apelin gene therapy with WJ-MSC cell therapy to treat type 2 diabetic rats effectively." (PMID 30526660, 2018). "Our results indicated that serum apelin levels are positively correlated with microalbuminuria in patients with type 2 diabetes." (PMID 23577111, 2013). "The results showed that serum apelin was significantly higher in the patients with type 2 diabetes compared to healthy people (p<0.05) and that urinary albumin was positively correlated with serum apelin (R = 0.78, p<0.05)." (PMID 23577111, 2013). "We were interested in determining if apelin in serum was higher in patients with type 2 diabetes, and we found that patients with type 2 diabetes had higher apelin concentrations compared to healthy people." (PMID 23577111, 2013). "In clinical studies, it has been reported that the levels of plasma apelin were elevated in insulin-resistant subjects and in morbidly obese individuals with type 2 diabetes, compared with normal controls." (PMID 23437347, 2013). "Urine microalbumin was measured after injecting KK mice (type 2 diabetes model) with apelin-13 or F13A to verify that apelin promoted albuminuria in DN." (PMID 23577111, 2013). "The results of our survival functions demonstrated that lower apelin levels are predictive of cardiovascular mortality in type 2 diabetic patients with a diagnosis of mild to moderate CKD." (PMID 24089668, 2013). "We also show for the first time that a key determinant of serum apelin levels is the basal disposition index, a surrogate measure of the two major defects in type 2 diabetes, defective insulin secretion and impaired insulin-sensitivity." (PMID 23227256, 2012). "In patients with type 2 diabetes, metformin increases apelin concentrations." (PMID 38887915, 2024). "Moreover, another research indicated that apelin injection reduces blood glucose levels, plasma insulin, and blood pressure in type 2 diabetic rats with hypertension." (PMID 38178017, 2024). "The authors concluded that the increased expression of apelin in patients with periodontitis and type 2 diabetes might indicate a possible role of this adipokine in inflammation and glucose regulation." (PMID 36902162, 2023). "COVID-19 infections lowered serum apelin concentrations in type 2 diabetes and hypertension." (PMID 37238973, 2023). "A hypothesis has been proposed that high apelin levels in people with type 2 diabetes might be a compensatory mechanism for decreased insulin sensitivity." (PMID 35610700, 2022). "We conduct a study to investigate whether serum apelin concentrations can predict MCI in type 2 diabetes in humans." (PMID 35610700, 2022). "There is a high expression of apelin in the aorta of type 2 diabetes rat models." (PMID 35355561, 2022). "However, decreased serum apelin levels were also observed in Type 2 diabetes, especially in newly diagnosed and untreated patients." (PMID 35610700, 2022).
type 2 diabetes (continued). "Moreover, in people with type II diabetes, there was a correlation between the concentration of apelin, glucose, and triglycerides in the plasma." (PMID 35011661, 2021). "Interestingly, patients who are obese or have type 2 diabetes show increased circulating Apelin levels, which suggests the possibility of Apelin resistance." (PMID 34326390, 2021). "Additionally, apelin levels have been found to be elevated in patients with type 2 diabetes and in the kidneys of diabetic mice." (PMID 32713238, 2020). "Studies have shown a decrease in apelin after 8 weeks of aerobic training at 60–70% maximum heart rate (HRmax) in middle-aged obese individuals and after 6 months of resistance training at 60–80% 1 repetition maximum (1RM) in type 2 diabetes patients." (PMID 30696454, 2019). "Moreover, insulin directly upregulates the expression of apelin, making this adipokine an attractive candidate to be studied in metabolic disorders such as type-2 diabetes." (PMID 24757680, 2014). "Therefore, we observed apelin/APLNR expression in kidneys from patients with type 2 diabetes as well as the correlation between albuminuria and serum apelin in patients with type 2 diabetes." (PMID 23577111, 2013). "However, several recent studies have shown decreased plasma apelin concentrations in newly diagnosed and untreated patients with type 2 diabetes." (PMID 23437347, 2013). "Therefore, it is hypothesized that apelin, which is increased in plasma in type 2 diabetes, lead to podocyte apoptosis through inhibiting podocyte autophagy, which resulted in podocyte dysfunction followed by DN." (PMID 28837139, 2017). "Therefore apelin could be proposed as an interesting therapeutic target in the treatment of type 2 diabetes." (PMID 25914650, 2015). "In addition, higher levels of apelin in patients with type 2 diabetes were observed." (PMID 23577111, 2013). "The relationship between apelin serum concentration and dysmetabolic conditions such as type 2 diabetes (T2D) is still controversial." (PMID 23227256, 2012). "However, in the beta cells of type 2 diabetes (T2D) db/db mice, the apelin level was detected to be upregulated." (PMID 35355561, 2022). "This study aimed to investigate the effects of oral administration of L‐carnitine (LC) on the expression of Apelin and APJ in adipose tissue of experimentally induced insulin‐resistant and type 2 diabetic rats." (PMID 33278072, 2020). "This study indicates that exercise training, despite the type, is an efficient method to modify apelin, APJ receptor, NO, and cardiotrophin-1 values in animals with type 2 diabetes." (PMID 32908933, 2020). "In this study, we report a novel approach to treat type 2 diabetic rats that combines apelin gene therapy with WJ-MSC cell therapy, which could provide a promising therapeutic option for management of type 2 diabetes clinically." (PMID 30526660, 2018). "In addition, we detected apelin and APLNR expression in the kidneys of type 2 diabetic mice (KK mice)." (PMID 23577111, 2013). "The results of this study demonstrate, in a large cohort of Italian subjects, that patients with type 2 diabetes have significantly increased serum apelin levels compared to non-diabetic individuals." (PMID 23227256, 2012).